HMGA2 (high mobility group AT-hook 2)
Diseases named in the same sentence as HMGA2 in open-access papers (continued):
Sharing a sentence is not in itself a finding about the gene and the disease.
colorectal cancer (continued). "Rather, an antihelminthic drug niclosamide has been repurposed and is selective against HMGA2-overexpressing colorectal cancer cells, reversing the HMGA2-driven gene signature, and inhibiting cell cycle-related genes in these cells." (PMID 32365712, 2020). "As an illustration, miR-4500 is downregulated and elicits an anti-cancer function through regulating HMGA2 expression in colorectal cancer." (PMID 32795273, 2020). "A similar effect was observed when siRNA- and miRNA-mediated silencing of HMGA2 induced apoptosis, G2/M cell cycle arrest, and suppressed proliferation and invasion of human colorectal carcinoma." (PMID 32365712, 2020). "A repurposing S100A4 inhibitor, niclosamide, was found to reverse the HMGA2-driven gene signature both in colorectal cancer cell lines and patients’ tissues." (PMID 31581665, 2019). "Previous reports indicated that high HMGA2 expression is involved in distant metastasis and poor prognosis in colorectal cancer." (PMID 31109142, 2019). "In vitro and in vivo experiments validated that HMGA2-overexpressing colorectal cancer cells were more sensitive to niclosamide." (PMID 31581665, 2019). "Nevertheless, our study provides a basis for treating HMGA2-overexpressing colorectal cancer by niclosamide, and the exact mechanism of action warrants further investigation." (PMID 31581665, 2019). "The aim of this study was to identify therapeutic agents selectively targeting HMGA2-overexpressing colorectal cancer." (PMID 31581665, 2019). "Together, our study repurposes an anthelminthic drug niclosamide for treating HMGA2-overexpression colorectal cancer." (PMID 31581665, 2019). "Bioinformatics analyses indicated that HMGA2-overexpressing colorectal cancers shift their dependency from HMGA2 to S100A4 that predicts a poor disease-free survival in colorectal cancer patients." (PMID 31581665, 2019). "In this study, a pan-cancer genomics survey based on Cancer Cell Line Encyclopedia (CCLE) and The Cancer Genome Atlas (TCGA) data indicated that HMGA2 was mainly overexpressed in gastrointestinal cancers including colorectal cancer." (PMID 31581665, 2019). "This study further supported the idea that the anticancer activity of HMGA2 inhibitors is limited by the endogenous expression of HMGA2 in colorectal cancer cells." (PMID 31581665, 2019). "Our integrated approach also included patient-derived xenografts of colorectal cancers and corroborated the role of HMGA2 as an important cancer cell-specific determinant of the efficacy of irinotecan." (PMID 31067275, 2019). "First, the gene expression profiles from HMGA2 overexpression of human colorectal cancer (CRC) DLD-1 cells were derived from the GEO dataset (GSE136544)." (PMID 31684108, 2019). "Here, we demonstrate a strong correlation between HMGA2 expression and chemosensitivity to 5-fluorouracil (5-FU), a widely used first-line systemic chemotherapy regimen for colorectal cancer (CRC) patients." (PMID 29515783, 2018). "In a mouse model of Wnt1-driven colorectal cancer, tumour formation was reduced in Hmga2−/− mice, suggesting a role for Hmga2 in cancer development." (PMID 30228296, 2018). "Tetrac inhibits the expression of the genes for β-catenin and high mobility group AT-hook 2 (HMGA2), and thus potentiates resveratrol-induced antiproliferation in colorectal cancer cells." (PMID 28934112, 2017). "Summary: miR-204 upregulates 5-Fu chemosensitivity via the downregulation of HMGA2 in colorectal cancer and provides significant insight into the mechanism of 5-Fu resistance in colorectal cancer patients." (PMID 27095441, 2016). "We also demonstrated that the miR-204/HMGA2 axis regulates colorectal cancer cell sensitivity to 5-Fu partly through the PI3K/AKT signaling pathway." (PMID 27095441, 2016).
colorectal cancer (continued). "Functional analyses showed that the miR-204/HMGA2 axis notably modulated cell proliferation and influenced the sensitivity of colorectal cancer cells to 5-fluorouracil (5-Fu)." (PMID 27095441, 2016). "Taken together, our present study elucidated that miR-204 upregulated 5-Fu chemosensitivity via the downregulation of HMGA2 in colorectal cancer and provided significant insight into the mechanism of 5-Fu resistance in colorectal cancer patients." (PMID 27095441, 2016). "Here, we revealed that miR-204 inhibited proliferation in colorectal cancer by directly targeting HMGA2." (PMID 27095441, 2016). "Further study on mechanism showed that the miR-204/HMGA2 axis played significant role on colorectal cancer development and progression via activating PI3K/AKT pathway." (PMID 27095441, 2016). "As far as the role of HMGA2 in colorectal cancer is concerned, the involvement of this gene is still controversial." (PMID 25859543, 2015). "Also, the correlation analysis between HMGA2 expression and patients survival would benefit the importance of HMGA2 in colorectal cancer therapy." (PMID 38845972, 2024). "In this study, we found that HMGA2 was overexpressed in colorectal cancer tissues." (PMID 38845972, 2024). "Additionally, the interaction between circNSUN2 and IGF2BP2 increases the stability of HMGA2 mRNA, leading to the promotion of liver metastasis in colorectal cancer." (PMID 38216996, 2024). "Hmga2 also induced M2 macrophage polarization in colorectal cancer by upregulating STAT3." (PMID 39769061, 2024). "Our results further highlight the importance of HMGA2 in colorectal cancer." (PMID 38845972, 2024). "M6A-modified circNSUN2 binds YTHDC1 (YTH domain-containing protein 1) and promotes its exit from the nucleus, further binding IGF2BP2 (lnsulin-like growth factor 2 mRNA-binding protein 2), which stabilizes HMGA2 (high mobility group AT-hook 2) mRNA, thus promoting colorectal cancer liver metastasis." (PMID 38329551, 2024). "This may affect the biological function of circRNAs, such as m6A modification of circNSUN2 could promote the liver metastasis of colorectal cancer by forming a circNSUN2/IGF2BP2/HMGA2 RNA-protein ternary complex." (PMID 37658417, 2023). "The downregulation of Hmga2 could sensitize colorectal cancer cells to oxaliplatin and promote drug-induced cell apoptosis by inactivating the PI3K/AKT pathway." (PMID 37963880, 2023). "By generating the RNA–protein ternary complexes of circNSUN2/IGF2BP2/HMGA2 and enhancing HMGA2 mRNA stability, circNSUN2 could facilitate the metastasis of colorectal cancer to the liver." (PMID 38102645, 2023). "Moreover, a potent mechanism whereby circNSUN2 can stabilize HMGA2 mRNA by forming an RNA-protein ternary complex has been raised in colorectal carcinoma." (PMID 37046045, 2023). "In the context of colorectal cancer, the depletion of HMGA2 could abrogate the promoting effects of miR-532-3p inhibitor on cell malignancy." (PMID 35031054, 2022). "It has been previously reported that circNSUN2 could enhance the stability of HMGA2 mRNA to promote colorectal carcinoma metastasis progression by forming a circNSUN2/IGF2BP2/HMGA2 RNA-protein ternary complex in the cytoplasm." (PMID 33853613, 2021). "We further examined whether Wnt/β-catenin inhibitors could exhibit selective cytotoxicity against HMGA2-overexpressing colorectal cancer cells." (PMID 31581665, 2019). "However, HMGA2 overexpression in colorectal cancer cells leads to an increased sensitivity to an anthelminthic drug niclosamide." (PMID 31581665, 2019).
colorectal cancer (continued). "Irinotecan is widely used in clinical practice, in particular to treat colon cancer patients, and we next asked whether expression of HMGA2 affected chemosensitivity to irinotecan in patient-derived xenograft (PDX) models of colorectal cancers." (PMID 31067275, 2019). "HMGA2 has been considered a therapeutic target in colorectal cancer." (PMID 31581665, 2019). "To investigate whether HMGA2 was a potential therapeutic target, we established a HMGA2-overexpressing DLD-1 colorectal cancer cell line." (PMID 31581665, 2019). "Further RNA sequencing analysis identified that niclosamide inhibited more cell-cycle-related gene expression in HMGA2-overexpressing colorectal cancer cells, which may explain its selective anticancer effect." (PMID 31581665, 2019). "Therefore, niclosamide indeed displayed selective in vitro and in vivo anticancer activity against HMGA2-overexpressing colorectal cancer." (PMID 31581665, 2019). "Interestingly, inhibition of S100A4 cannot fully explain the sensitizing effect of niclosamide on HMGA2-overexpressing colorectal cancer cells, suggesting that additional mechanisms are involved." (PMID 31581665, 2019). "For example, HMGA2 silencing by small interfering (si)RNA, shRNA and micro(mi)RNA (such as miR-204 and miR-4500) was shown to inhibit cell growth and induce apoptosis in human colorectal cancer cells." (PMID 31581665, 2019). "Therefore, we employed CMap analysis to investigate the genetic dependency of HMGA2-overexpressing colorectal cancer." (PMID 31581665, 2019). "Our study provides a novel therapeutic strategy for HMGA2-overexpressing colorectal cancer." (PMID 31581665, 2019). "To determine whether HMGA2 increased chemoresistance to 5-FU in vivo, we used a colorectal cancer xenograft model." (PMID 29515783, 2018). "MiR-204 plays key roles in colorectal cancer development and progression, by repressing colorectal cancer cell growth as well as by promoting colorectal cancer cell sensitivity to a chemotherapeutic drug (5-Fu) through directly targeting HMGA2." (PMID 27095441, 2016). "Finally, it has been also reported that HMGA2 overexpression promotes metastasis formation and affects survival of colorectal cancer patients." (PMID 25859543, 2015). "m6A circNSUN2 regulates cytoplasmic export and stabilizes HMGA2 to promote colorectal carcinoma (CRC) liver metastasis (LM); In colorectal cancer, another METTL3-induced circ1662 promoted CRC cell invasion and migration by accelerating YAP1 nuclear transport." (PMID 36861189, 2023). "Along with let-7 expression, HMGA2 has been determined to be a predictive biomarker of poor clinical outcomes in many epithelial and hematopoietic malignancies including acute myeloid leukemia, ovarian and colorectal carcinoma, and oral squamous cell carcinoma." (PMID 32365712, 2020). "In addition, HMGA2-overexpressing colorectal cancer cell lines did not display higher susceptibility to a previously identified HMGA2 inhibitor (netroposin)." (PMID 31581665, 2019). "In addition, the HMGA2 protein is overexpressed in various types of cancer, including lung cancer, ovarian cancer, breast cancer, oral squamous cell carcinoma, pancreatic cancer, and colorectal cancer." (PMID 31684108, 2019). "Therefore, we speculated that other mechanisms, in addition to Wnt/β-catenin and S100A4 inhibition, may involve in the selective anticancer effect of niclosamide against HMGA2-overexpressing colorectal cancer cells." (PMID 31581665, 2019). "Therefore, we speculated that niclosamide tends to interfere with cell cycle progression and DNA repair pathways in HMGA2-overexpressing colorectal cancer, which may account for its higher cytotoxicity." (PMID 31581665, 2019).
colorectal cancer (continued). "Therefore, we speculated that S100A4 inhibition by niclosamide may exhibit therapeutic benefit for HMGA2-overexpressing colorectal cancer." (PMID 31581665, 2019). "Therefore, we thought that S100A4 might serve as a potential therapeutic target for HMGA2-overexpressing colorectal cancer." (PMID 31581665, 2019). "However, subgroup analyses revealed that the high expressed HMGA2 was associated with poor OS in head and neck cancer, gastric cancer and colorectal cancer, but not esophageal cancer and ovarian cancer." (PMID 29997523, 2018). "In the present study, we showed miR-204 could promote the sensitivity of colorectal cancer cells to the most commonly used drug (5-Fu) for colorectal cancer by targeting HMGA2, which suggested significant potential for miR-204/HMGA2 signaling in cell viability regulation." (PMID 27095441, 2016). "Therefore, our study demonstrates the importance of miR-204/HMGA2 signaling in colorectal cancer tumorigenesis and suggests that targeting this signaling may represent a new therapeutic approach for human colorectal cancer." (PMID 27095441, 2016). "For example, in colorectal cancer (CRC), the m6A reader YTHDC1 promotes the export of circNSUN2 to the cytoplasm, where it forms a circNSUN2/IGF2BP2/HMGA2 RNA–protein complex that stabilizes HMGA2 mRNA." (PMID 39095902, 2024). "Under the condition of colorectal cancer, long noncoding RNA PiHL epigenetically activated HMGA2 transcription by relieving EZH2 on HMGA2, thus promoting PI3K/AKT phosphorylation." (PMID 35264108, 2022). "It was further reported that miR-1249 suppresses colorectal cancer (CRC) angiogenesis by targeting both VEGFA and HMGA2 through the AKT/mTOR signaling pathway." (PMID 33668453, 2021). "A HSP90 inhibitor NVP-AUY922 is able to reduce HMGA2 expression and suppress HMGA-mediated EMT in colorectal cancer cells." (PMID 31581665, 2019). "To determine whether HMGA2 affects cell sensitivity toward PTX, we treated colorectal cancer cells with PTX." (PMID 38845972, 2024). "Additionally, m6A modification of circNSUN2 contributes to colorectal cancer liver metastasis by inducing its cytoplasmic export and the formation a circNSUN2/IF2BP2/HMGA2 complex that stabilizes HMGA2." (PMID 38184597, 2024). "In this study, we found a higher expression of HMGA2 in colorectal cancer tissue than in the para-nontumor parts, and decreased cell growth was also confirmed." (PMID 38845972, 2024). "In addition, accumulating evidence has demonstrated the role of HMGA2 in EMT in several cancers, including prostate cancer and colorectal cancer." (PMID 37445942, 2023). "For example, circNSUN2, an abnormally expressed circRNA in colorectal carcinoma (CRC) tissues, could regulate the stability of HMGA2 mRNA by binding to IGF2BP2, resulting in cancer progression." (PMID 37592296, 2023). "In addition, circNSUN2 can bind to IGF2BP2 and HMGA2, forming the circNSUN2/IGF2BP2/HMGA2 RNA–protein ternary complex, which contributes to promoting colorectal carcinoma metastasis." (PMID 37723588, 2023). "Since MALAT1 is known to sponge miR-26b to promote invasion and metastasis of colorectal cancer, we expected that MALAT1 might also sponge miR-26b in BC, and that miR-26b targets and down-regulates HMGA2." (PMID 34419065, 2021). "Moreover, aspirin reduces mTOR signaling by inhibiting the mTOR effectors S6K1 and 4EBP1 in colorectal cancer and suppresses esophageal squamous cell carcinoma growth by inhibiting HBXIP and HMGA2." (PMID 34414020, 2021). "Similarly, miR-1249 suppresses the growth, metastasis, and angiogenesis of colorectal cancer cells (HCT116, HT29, SW480, SW620, HCT8, and DLD-1) by targeting VEGFA and HMGA2." (PMID 34439740, 2021). "In this study based on the integration of bioinformatics analyses and in vitro/in vivo experimental validation, we found that HMGA2 is not a suitable prognostic biomarker and therapeutic target in colorectal cancer." (PMID 31581665, 2019).
colorectal cancer (continued). "However, knockdown of HMGA2 by siRNA increases the sensitivity of colorectal cancer cells to NVP-AUY922, whereas HMGA2 overexpression attenuates the anticancer effect of NVP-AUY922." (PMID 31581665, 2019). "Low HMGA2 expression was also linked to microsatellite instability (p = 0.0002) and BRAF mutations (p = 0.0018) as well as absence of RAS mutations (p < 0.0001) in colorectal cancer and HPV infection in squamous cell carcinomas (p < 0.0001)." (PMID 40518465, 2025). "Specific small non-coding circular RNAs (circNSUN2) promotes EMT and human and mouse colorectal cancer (CRC) cell metastasis by stabilizing high levels of cytoplasmic HMGA2 RNA-protein interactions in a circNSUN2/IGF2BP2/HMGA2/ complex and activating the HMGA2 pathway." (PMID 32365712, 2020). "In colorectal cancer, miR-1249-3p may present as a novel therapeutic candidate based on its inhibitory actions in tumor growth, metastasis, and angiogenesis by targeting vascular endothelial growth factor A (VEGFA) and high mobility group AT-hook 2 (HMGA2)." (PMID 31769433, 2019). "In addition, CPX induces cytotoxicity of colorectal cancer (CRC) cells by induction of cell cycle arrest and apoptosis in vitro and in vivo through direct interaction with the AT-hook motif (a small DNA-binding protein motif) of HMGA2." (PMID 31684108, 2019). "Therefore, our results argued that HMGA2 may not a suitable prognosis biomarker and therapeutic target for colorectal cancer." (PMID 31581665, 2019). "However, a recent study found that netropsin was not selectively cytocidal to only HMGA2-overexpressing colorectal cancer cells, and its potential binding to other AT-hook DNA domains might introduce off-target side-effects, making it therapeutically inefficient." (PMID 32365712, 2020). "However, S100A4 knockdown did not exhibit higher cytotoxicity in DLD-1-HMGA2 cells as niclosamide did, confirming that S100A4 downregulation was not sufficient to selectively kill HMGA2-overexpressing colorectal cancer cells." (PMID 31581665, 2019).